SERPINF2 (serpin family F member 2)
Description:
Serine protease inhibitor. The major targets of this inhibitor are plasmin and trypsin, but it also inactivates matriptase-3/TMPRSS7 and chymotrypsin.
Synonyms: Alpha-2-PI; AAP; PLI; API; A2AP; alpha2AP
Tractability: Antibody: its Gene Ontology location is reachable by antibodies, with high confidence; UniProt places it where antibodies can reach, with medium confidence; UniProt predicts a signal peptide or a membrane-spanning region. PROTAC: ubiquitination databases record sites on it; its protein half-life has been measured.
Gene: Protein-coding gene on chromosome 17 (1,742,069 to 1,755,271, forward strand). Ensembl gene ENSG00000167711.
Subcellular location: Secreted
Subcellular location (Human Protein Atlas): Golgi apparatus; Predicted to be secreted
Pathways (Reactome):
Hemostasis: Dissolution of Fibrin Clot; Platelet degranulation
Gene Ontology:
Molecular function: endopeptidase inhibitor activity; protease binding; protein binding; protein homodimerization activity; serine-type endopeptidase inhibitor activity
Biological process: negative regulation of fibrinolysis; negative regulation of plasminogen activation; positive regulation of cell differentiation; positive regulation of collagen biosynthetic process; positive regulation of ERK1 and ERK2 cascade; positive regulation of JNK cascade; positive regulation of stress fiber assembly; positive regulation of transcription by RNA polymerase II; positive regulation of transforming growth factor beta production; blood vessel morphogenesis; collagen fibril organization; fibrinolysis; maintenance of blood vessel diameter homeostasis by renin-angiotensin; positive regulation of cell-cell adhesion mediated by cadherin; positive regulation of coagulation; positive regulation of smooth muscle cell proliferation
Cellular component: blood microparticle; cell surface; extracellular exosome; extracellular matrix; extracellular region; fibrinogen complex; platelet alpha granule lumen
Genetic constraint (gnomAD): Loss-of-function variants: 15 observed, 43.59 expected, observed/expected ratio (o/e) 0.34, 90% interval 0.23 to 0.53. The upper end of that interval is the gene's LOEUF score, 0.53, which puts it in group 2 of 6, group 1 being the genes least tolerant of losing a copy. Missense variants: 499 observed, 626.09 expected, observed/expected ratio (o/e) 0.8, 90% interval 0.74 to 0.86. Synonymous variants: 275 observed, 274.64 expected, observed/expected ratio (o/e) 1, 90% interval 0.91 to 1.11.
Gene-disease validity (ClinGen):
ClinGen rates the evidence that SERPINF2 causes each of these diseases.
alpha-2-plasmin inhibitor deficiency (autosomal recessive): Definitive.
Homologues: Orthologues: chimpanzee SERPINF2 (99% identical), macaque SERPINF2 (94% identical), rabbit SERPINF2 (82% identical), dog SERPINF2 (82% identical), pig SERPINF2 (81% identical), guinea pig SERPINF2 (79% identical), mouse Serpinf2 (75% identical), rat Serpinf2 (72% identical), tropical clawed frog serpinf2 (36% identical), zebrafish serpinf2b (34% identical), zebrafish serpinf2a (33% identical). Paralogues in human: SERPING1 (25% identical), SERPINF1 (24% identical), SERPINA3 (23% identical), SERPINB1 (23% identical), SERPINB11 (23% identical), SERPINC1 (22% identical), SERPINB8 (22% identical), SERPINB9 (22% identical), SERPINA5 (21% identical), SERPINA1 (21% identical), SERPINA4 (21% identical), SERPINB7 (21% identical), and 24 more.
Diseases named in the same sentence as SERPINF2 in open-access papers:
SERPINF2 is named in the same sentence as 71 diseases in open-access papers, as found by Europe PMC text mining. Sharing a sentence is not in itself a finding about the gene and the disease. The quoted sentences say what the papers report.
COVID-19 (9 papers, 2021 to 2024). A disease caused by infection with severe acute respiratory syndrome coronavirus 2. "Mutations in SERPINF2 can cause severe bleeding disorders and upregulation of SERPINF2 is implicated in COVID-19 patient thrombosis." (PMID 34616619, 2021). "A recent study revealed that SERPINF2 expression increases in serum levels of patients with COVID-19, along with several other SERPINs (SERPINA1 and SERPINA3)." (PMID 36690780, 2023). "In our results, F11, F9, FGG, FGA, SERPINA5, SERPINC1, and SERPINF2 are involved in the coagulation cascade, and significantly higher expressed in COVID-19-children compared with COVID-19-adults." (PMID 34335977, 2021). "On the contrary, we found a number of plasma serine protease inhibitors such as SERPINA5, SERPINC1, and SERPINF2, which negatively regulate the blood coagulation cascade 29, were strongly up-regulated in COVID-19-children against in healthy children or COVID-19-adults." (PMID 34335977, 2021).
thrombosis (8 papers, 2011 to 2025). "SERPINF2 is an obvious candidate for venous thrombosis as it codes for a serpin protease inhibitor that acts as an inhibitor of plasmin." (PMID 37098010, 2023). "Coagulation-related factors, such as F2, SERPIND1, SERPINF2, SERPINA3, FGA, FGB, and FGG, are also downregulated, leading to coagulation dysfunction in the body, which is not conducive to post-exercise recovery and can even lead to thrombosis in severe cases." (PMID 40646880, 2025).
Alzheimer disease (3 papers, 2022 to 2025). A progressive, neurodegenerative disease characterized by loss of function and death of nerve cells in several areas of the brain leading to loss of cognitive function such as memory and language. "Therefore, our study provides causal evidence for SERPINF2 protein as a potential regulatory factor for Alzheimer's disease for the first time." (PMID 40186323, 2025). "There is evidence that the dysregulation of serpins is involved in Alzheimer’s disease and prion diseases; for instance, in mice infected with prions, elevated levels of SerpinF2 were observed compared to controls." (PMID 40373086, 2025). "The mutation or loss of Ash1L may cause autistic-like behaviors; and low expression of Serpinf2 is related to Alzheimer’s disease." (PMID 35237591, 2022).
myocardial infarction (3 papers, 2016 to 2023). Gross necrosis of the myocardium, as a result of interruption of the blood supply to the area, as in coronary thrombosis. "In a previous study, higher SerpinF2-levels in EVs were related to an increased risk for myocardial infarction and vascular mortality." (PMID 26820481, 2016). "Higher levels of α2-antiplasmin have been reported in healthy people compared to age-matched individuals with myocardial infarction, which could support the present findings of higher SERPINF2 levels in healthy centenarians compared to diseased controls." (PMID 32100723, 2020).
Stroke (3 papers, 2019 to 2024). Sudden impairment of blood flow to a part of the brain due to occlusion or rupture of an artery to the brain. "Some of the stroke subtype-specific proteins (FBLN1, F2, SERPINF2, CBP2, FCN3, GPX3, IKG, and GSN) were also affected by the CBS deficiency." (PMID 31242583, 2019).
thrombotic disease (3 papers, 2014 to 2022). The formation of a blood clot in the lumen of a vessel or heart chamber; causes include coagulation disorders and vascular endothelial injury. "There is increasing evidence that SERPINF2 is a useful alternative target in the development of new therapeutics for thrombotic diseases." (PMID 24659849, 2014). "α2AP (SERPINF2) is the principal inhibitor of plasmin, which is responsible for fibrinolysis and has been investigated as a target for treatment of thrombotic diseases." (PMID 36260611, 2022).
diabetes (2 papers, 2018 to 2023). "SERPINF2 modulates insulin sensitivity and is associated with cardiovascular diseases and diabetes." (PMID 29992704, 2018).
heart failure (2 papers, 2016 to 2020). Inability of the heart to pump blood at an adequate rate to meet tissue metabolic requirements. "SerpinG1 and SerpinF2 were associated with heart failure in, respectively, two and one out of three EV sub‐fractions and in plasma, but not with renal dysfunction." (PMID 32648717, 2020). "Previously, we reported that EV protein levels of Cystatin C, CD14, SerpinG1, and SerpinF2 were associated with heart failure in dyspnoeic patients." (PMID 32648717, 2020). "Higher SerpinF2 levels were also associated with decreased risk of heart failure in LDL sub‐fraction and in plasma." (PMID 32648717, 2020). "In the current study, we found that both SerpinG1 and SerpinF2 were associated with heart failure." (PMID 32648717, 2020). "Extracellular vesicle levels of CD14, SerpinG1 and SerpinF2 are associated with the occurrence of heart failure in subjects suspected for acute heart failure, suggesting common underlying pathophysiological mechanisms for heart failure and vascular events." (PMID 26820481, 2016). "The primary aim of this study is to investigate the association between the selected EV proteins (Cystatin C, CD14, SerpinG1, and SerpinF2) with both renal dysfunction and heart failure in patients with acute dyspnoea." (PMID 32648717, 2020). "Furthermore, extracellular vesicle CD14- and SerpinF2-levels were significantly higher in heart failure patients with preserved ejection fraction than in those with reduced ejection fraction." (PMID 26820481, 2016). "Because SerpinF2 reduces fibrinolysis by inhibiting plasmin, this suggests that there may be increased fibrinolytic activity in patients with heart failure; however, how/if this relates to the relative risks of bleeding versus thrombosis in heart failure remains to be investigated." (PMID 32648717, 2020). "After adjustment for confounders, levels of TEX SerpinG1 (aOR 1.55, p = 0.004) and SerpinF2 (aOR 0.71, p = 0.021) remained statistically significantly related to heart failure, whereas CD14 and CystatinC TEX-levels did not." (PMID 26820481, 2016). "Interestingly, patients with heart failure have lower SerpinF2 levels as compared with those without heart failure." (PMID 32648717, 2020). "According to these results, SerpinG1 and SerpinF2 seem to be markers for heart failure rather than for renal dysfunction, suggesting that the complement and fibrinolysis pathways may be more important pathophysiologically in development of heart failure than renal dysfunction." (PMID 32648717, 2020).
leukaemia (2 papers, 2024). "In line with the mouse experiments, high SERPINF2 expression in leukemia cells was associated with a significant survival extension in patients with B-ALL." (PMID 39567540, 2024). "In addition, SERPINF2 expression in leukemia cells was significantly lower in patients with B-ALL compared to AML, but significantly higher in BCR-ABL1+ B-ALL cells versus healthy BM." (PMID 39567540, 2024).
nephrotic syndrome (2 papers, 2016 to 2022). A collection of symptoms that include severe edema, proteinuria, and hypoalbuminemia; it is indicative of renal dysfunction. "Plasma SerpinF2 is mainly produced in the liver and kidney and was found to be reduced in patients with nephrotic syndrome." (PMID 26820481, 2016).
prion disease (2 papers, 2022 to 2025). A transmissible disease that is caused by a protein that is able to induce abnormal folding of normal cellular proteins, leading to characteristic spongiform brain changes, which are associated with neuronal loss without an inflammatory response. "However, few studies have explored the putative role of SerpinF2 in prion diseases." (PMID 35416570, 2022).
Sepsis (2 papers, 2014 to 2025). Sepsis is defined as life-threatening organ dysfunction caused by a dysregulated host response to infection. "Antithrombin III (SERPINC1) as well as Alpha-2-antiplasmin (SERPINF2) are both important regulators of the coagulation cascade and were reported to be associated with sepsis mortality and organ dysfunction." (PMID 40898225, 2025). "We observed an increased SERPINA1 (P < 0.05) and decreased SERPINF2 (P < 0.05) in the PF patient compared with the healthy individuals and the burn sepsis patients, which was similar to the HPLC-chip/MS results." (PMID 24659849, 2014).
B-cell acute lymphoblastic leukemia (1 paper, 2025). A neoplasm of lymphoblasts committed to the B-cell lineage, typically composed of small to medium-sized blast cells. "SERPINF2 protein expression was upregulated in B-cell acute lymphoblastic leukemia but downregulated in low-grade USCSs." (PMID 40666499, 2025).
breast carcinoma (1 paper, 2022). "The protein product of SERPINF2 has been found in the serum of breast cancer patients when evaluating treatment response; however, this protein appeared in both resistant and sensitive groups." (PMID 36338974, 2022). "SERPINF2 is differentially expressed in breast cancer tissues compared with normal tissues." (PMID 36338974, 2022).
diabetic retinopathy (1 paper, 2021). "Proteomics analysis has identified multiple proteins in the serpin family including both Serpinc1 and Serpinf2 as potential serum biomarkers of retinal inflammation in diabetic retinopathy." (PMID 34440888, 2021).
Disseminated intravascular coagulation (1 paper, 2023). Disseminated intravascular coagulation is characterized by the widespread activation of coagulation, which results in the intravascular formation of fibrin and ultimately thrombotic occlusion of small and midsize vessels. "SERPINF2 (α2AP) shows altered levels in falciparum malaria patients, contributing to the development of disseminated intravascular coagulation and increasing the risk of thrombosis." (PMID 37638001, 2023).
endometriosis (1 paper, 2021). The growth of functional endometrial tissue in anatomic sites outside the uterine body.
eosinophilia (1 paper, 2023). "The results of the biomarker analysis showed that periostin, PAPP-A, CST-2, SerpinF2 and eosinophilia showed similar courses to NPS." (PMID 36969262, 2023).
head and neck cancer (1 paper, 2023). A primary or metastatic malignant neoplasm affecting the head and neck. "In addition, serpins were associated with head and neck cancer; in particular, it has been reported that SERPINA1 is associated with tumor progression, while SERPINC1 and SERPINF2 are correlated with a good response to radiotherapy, and these data are in good agreement with our results." (PMID 37371031, 2023).
Left ventricular diastolic dysfunction (1 paper, 2022). Abnormal function of the left ventricule during left ventricular relaxation and filling. "SERPINF1 strongly inhibits angiogenesis, and SERPINF2 is involved in alpha-2-plasmin inhibitor deficiency, vasculitis, and left ventricular diastolic dysfunction." (PMID 35990977, 2022).
psoriasis (1 paper, 2022). An autoimmune condition characterized by red, well-delineated plaques with silvery scales that are usually on the extensor surfaces and scalp. "A few DEPs, such as SERPINC1, SERPINF2, F2, PLXDC2, and TYMP, were also involved in regulating blood coagulation and angiogenesis, which plays an essential role in the pathogenesis and maintenance of psoriasis." (PMID 36483564, 2022).
renal dysfunction (1 paper, 2020). "Given the relevance of renal dysfunction, inflammation, and the coagulation system in the development of cardiovascular diseases, we extended previous work on Cystatin C, CD14, SerpinG1, and SerpinF2 within circulating EVs to explore their possible associations with the CRS." (PMID 32648717, 2020).
serous ovarian cancer (1 paper, 2024). "Previous studies have indicated a correlation between SERPINF2 with unfavorable outcomes in advanced serous ovarian cancer, and laboratory tests have confirmed its crucial involvement in tumor growth and spread." (PMID 38751445, 2024).
tumor (9 papers, 2016 to 2026). "Specifically, tumor tissues show increased expression of SERPINA1, RASGRP1, and CFB compared to normal tissues, whereas C1S, SERPINF2, and TLN2 display the opposite pattern." (PMID 38751445, 2024). "SERPINF2 expression was independent of patient sex and tumor stage and clearly distinguished tumor from normal bile duct tissue." (PMID 41892837, 2026).
cancer (5 papers, 2017 to 2025). A tumor composed of atypical neoplastic, often pleomorphic cells that invade other tissues. "Several other acute-phase response proteins were also elevated towards diagnosis (e.g., HP, ORM1, ORM2, CRP, SERPINF2), presumably due to a host systemic inflammatory response—a known prognostic indicator in cancer patients." (PMID 29232830, 2017).
infection (5 papers, 2014 to 2024). The state of being infected such as from the introduction of a foreign agent such as serum, vaccine, antigenic substance or organism. "This was confirmed at the protein level, as infection decreased the amount of secreted AHSG and apolipoproteins APOA1, APOE and APOH, in both HepG2 and Huh7 conditioned media, as well as of APOB, APOC3 and SERPINF2 in Huh7." (PMID 34858876, 2021).
SERPINF2 also shares sentences with these, for which no sentence is quoted: bleeding disorders (3 papers); glaucoma (3); ischemic stroke (3); pulmonary embolism (3); schizophrenia (3); cardiovascular diseases (2); cognitive decline (2); endothelial dysfunction (2); fibrosis (2); liver fibrosis (2); lupus (2); systemic sclerosis (2); abscess (1); acute myocardial infarction (1); adenoma (1); age (1); Anxiety (1); Arterial thrombosis (1); atransferrinemia (1); Cerebral ischemia (1); coagulopathy (1); cognitive disorder (1); corneal ulcer (1); dementia (1); depression (1); diabetic nephropathy (1); falciparum malaria (1); hemochromatosis (1); hypogonadism (1); infectious disease (1).
A further 15 diseases each share a sentence with SERPINF2 in 1 paper.